FGFR1 (fibroblast growth factor receptor 1)
Diseases named in the same sentence as FGFR1 in open-access papers (continued):
Sharing a sentence is not in itself a finding about the gene and the disease.
asthma (1 paper, 2024). "While these data would have provided additional context and depth to our findings, the focus of our research was on exploring the molecular mechanisms underlying FGFR1 methylation in asthma." (PMID 39377013, 2024). "Dual-luciferase and DNA methylation inhibition assays were performed to elucidate the underlying mechanism of FGFR1 gene in asthma." (PMID 39377013, 2024). "Our findings indicate that FGFR1 hypomethylation amplifies NF-κB signaling, contributing to the inflammatory processes linked to asthma." (PMID 39377013, 2024). "Inhibiting FGFR1 has been shown to downregulate the expression of genes associated with asthma pathogenesis, including SOX2, a marker of epithelial-mesenchymal transition (EMT), as well as the mesenchymal markers N-cadherin and Vimentin." (PMID 39377013, 2024). "Despite these constraints, our study underscores the potential importance of FGFR1 demethylation in activating NF-ĸB signaling, which could exacerbate the pathological inflammation associated with asthma." (PMID 39377013, 2024). "This study aims to investigate how DNA methylation-mediated silencing of FGFR1 contributes to the enhancement of NF-κB signaling, thereby influencing the progression of asthma." (PMID 39377013, 2024). "RT-qPCR was utilized to assess FGFR1 mRNA levels in the serum of asthma patients and BEAS-2B, HBEpiC, and PCS-301-011 cells." (PMID 39377013, 2024). "By establishing a connection between FGFR1 methylation and NF-κB activity, our study offers fresh insights into the molecular mechanisms of asthma and proposes potential targets for therapeutic strategies." (PMID 39377013, 2024). "Given that epigenetic regulation, particularly DNA methylation, plays a significant role in asthma by modulating gene expression, we aimed to investigate the interaction between FGFR1 and NF-κB signaling in bronchial epithelial cells." (PMID 39377013, 2024). "To delve deeper into the contribution of FGFR1 in asthma progression, we conducted experiments involving the overexpression of FGFR1 in BEAS-2B cells to investigate its interplay with NF-ĸB." (PMID 39377013, 2024). "A recent bioinformatics analysis identified FGFR1 as a potential dysregulated gene in asthma based on consensus gene expression patterns." (PMID 39377013, 2024). "The impact of 5-Aza-CdR on FGFR1 expression was assessed by investigating FGFR1 DNA methylation in five asthma cases and five healthy controls." (PMID 39377013, 2024). "Specifically, we examined the effect of 5-Aza-CdR, a DNA methylation inhibitor, on this regulatory axis in BEAS-2B cells, following evidence of elevated FGFR1 expression in asthma patients." (PMID 39377013, 2024). "Elevated levels of FGFR1 expression in airway epithelial cells suggest its involvement in airway remodeling, a significant characteristic of asthma." (PMID 39377013, 2024). "Despite these findings, the precise role of FGFR1 in bronchial epithelial cells and its mechanisms contributing to asthma pathogenesis remain inadequately elucidated." (PMID 39377013, 2024). "Methylation analysis showed hypomethylation of the FGFR1 DNA promoter in asthma samples compared to healthy controls." (PMID 39377013, 2024). "DNA methylation of FGFR1 inactivates the NF-ĸB signaling pathway, suggesting a promising avenue for developing effective therapeutic strategies for asthma." (PMID 39377013, 2024). "Our findings suggest that extracellular RNA and DNA, particularly through the mechanism of DNA methylation, play a significant role in the regulation of FGFR1 expression and the activation of NF-ĸB signaling in asthma." (PMID 39377013, 2024). "Higher levels of FGFR1 mRNA were observed in the serum of asthma patients compared to healthy controls in our study." (PMID 39377013, 2024). "Elevated FGFR1 mRNA levels were observed in the serum of asthma patients compared to healthy controls." (PMID 39377013, 2024). "Our findings reveal a potential mechanism involving FGFR1 in the progression of asthma." (PMID 39377013, 2024).
asthma (continued). "Notably, our comparison of asthma and healthy samples showed a significant increase in FGFR1 mRNA levels in asthma samples, supporting the notion of FGFR1’s involvement in asthma progression." (PMID 39377013, 2024). "Fibroblast growth factor receptor 1 (FGFR1) is known to play a crucial role in the pathogenesis of asthma, although the precise mechanism remains unclear." (PMID 39377013, 2024). "Additionally, we assessed the clinical relevance of DNA methylation in regulating FGFR1 expression in the serum of asthma patients." (PMID 39377013, 2024). "Our findings suggest that DNA methylation of FGFR1 may be a key epigenetic mechanism through which environmental factors influence asthma development." (PMID 39377013, 2024). "Therefore, our study not only underscores the importance of FGFR1 methylation in asthma but also emphasizes the broader role of epigenetic mechanisms in mediating gene-environment interactions, offering new insights into potential intervention strategies." (PMID 39377013, 2024). "Given that epigenetic modifications are responsive to environmental changes, the observed hypomethylation of FGFR1 in asthma patients could reflect an interaction between genetic susceptibility and environmental exposures." (PMID 39377013, 2024). "Additionally, a decrease in methylation levels in the FGFR1 DNA promoter was detected in the serum of asthma patients using the MassARRAY technique." (PMID 39377013, 2024). "Our findings contribute to the understanding of asthma’s molecular complexity by suggesting that FGFR1 hypomethylation and the subsequent activation of NF-κB signaling may be associated with specific asthma endotypes, particularly those linked to airway remodeling and chronic inflammation." (PMID 39377013, 2024). "FGFR1 plays a central role in modulating epithelial-mesenchymal signaling dysregulation, which may be a shared pathophysiological mechanism among individuals with different asthma severities." (PMID 39377013, 2024). "The hypomethylation observed in the extracellular DNA of FGFR1 suggests that DNA methylation may serve as a crucial regulatory mechanism, influencing gene expression and the progression of inflammatory processes in asthma." (PMID 39377013, 2024). "The recent study indicates that upregulated FGFR1 expression in H1581 and DMS114 cells induces epithelial-mesenchymal transition (EMT), potentially contributing to asthma pathology." (PMID 39377013, 2024).
benign fibrous histiocytoma (1 paper, 2024). A benign neoplasm composed of fibroblastic spindle cells in a whorled storiform pattern. "Non-ossifying fibroma/benign fibrous histiocytoma, KRAS and FGFR1 mutations were confirmed." (PMID 39850815, 2024).
biliary tract cancer (1 paper, 2025). "Tasurgratinib, a selective FGFR1–3 inhibitor, was approved in Japan in 2024 for second-line treatment of FGFR2 fusion-positive biliary tract cancer." (PMID 40565050, 2025).
bone osteosarcoma (1 paper, 2014). A usually aggressive malignant bone-forming mesenchymal neoplasm arising from the bone. "Of the total cohort of 288 patients, 22 had a radiation-induced bone osteosarcoma, 3 (13.6%) of which showed FGFR1 gene amplification." (PMID 24861215, 2014). "One of 57 (1.7%) bone osteosarcomas not treated with neo-adjuvant chemotherapy, and one radiation-induced osteosarcoma of 19 (5.3%) bone osteosarcomas on which treatment information was not available also revealed FGFR1 amplification." (PMID 24861215, 2014).
brachydactyly (1 paper, 2025). A disease characterized by the presence of brachydactyly, including syndromic and non-syndromic forms. "Functional protein association network analysis demonstrates a strong association of BMP8A and FGFR1 with other brachydactyly disease‐causing genes." (PMID 41036481, 2025).
brainstem tumors (1 paper, 2024). "Previous studies also demonstrated that PDGFRA amplification occurred more frequently in brainstem tumors, while fibroblast growth factor receptor 1 (FGFR1) mutation was usually limited in the thalamus." (PMID 38644565, 2024).
carcinosarcoma (1 paper, 2025). A malignant tumor composed of a mixture of carcinomatous and sarcomatous elements. "Given the precedence in targeting ERBB2-amplified/HER2-expressing carcinosarcoma, we focused our attention on FGFR1 copy number gain/amplification as another potentially targetable alteration in carcinosarcoma." (PMID 41202566, 2025). "In our present cohort of 6 gynecologic carcinosarcoma PDX models, AB740 demonstrated high copy number gain (8 copies) of FGFR1 with the highest FGFR1 protein expression by immunoblot analysis compared to the other tumors." (PMID 41202566, 2025).
cerebral tumors (1 paper, 2017). "Increased FGFR1 and/or FGFR3 expression was therefore a common characteristic of cerebral tumors." (PMID 28468611, 2017).
cerebrovascular diseases (1 paper, 2024). "Genes related to cardiovascular and cerebrovascular diseases annotated by the PI3K-Akt signaling pathway included Fgf12, Fgfr1, PDGFA, and PDGFRα." (PMID 38195688, 2024).
cervical tumors (1 paper, 2025). "The same occurred in the NCI-MATCH (National Cancer Institute-molecular analysis for therapy choice) trial of tumors such as breast, urothelial, and cervical tumors with FGFR1-3 aberrations, as fexagratinib showed modest benefit only in patients with FGFR1-3 point mutations or fusions." (PMID 40283927, 2025).
choanal atresia (1 paper, 2012). Choanal atresia (CA) is a congenital anomaly of the posterior nasal airway characterized by the obstruction of one (unilateral) or both (bilateral) choanal aperture(s), with clinical manifestations ranging from acute respiratory distress to chronic nasal obstruction. "Developmental defects of GnRH neurons and the olfactory bulb are associated with hyposmia, rarely associated with the clinical phenotypes of synkinesia, cleft palate, ear anomalies, or choanal atresia, and may be due to mutations of KAL1, FGFR1/FGF8, PROKR2/PROK2, or CHD7." (PMID 22229029, 2012).
chondrodysplasia (1 paper, 2025). "In addition to the chondrodysplasia phenotype, we investigated the potential impact of FGFR1 p.N330I on phosphate wasting, which is a manifestation of OGD patients with this variant." (PMID 41473314, 2025).
coloboma (1 paper, 2018). An abnormality in which a part of a structure in one or both eyes is missing. "A previous report also suggested functional interactions between these genes, as CHH patients with mutations in FGFR1 and CHD7 exhibit overlaps in associated phenotypes (cleft lip/palate, coloboma or ear anomalies)." (PMID 29419413, 2018).
congenital malformations (1 paper, 2021). "The CHD7- and FGFR1-positive patient group was significantly enriched by additional non-reproductive congenital malformations." (PMID 34198905, 2021).
Cryptozoospermia (1 paper, 2023). A type of oligozoospermia in which spermatozoa can be detected in an ejaculate only after centrifugation and inspection of the pellet. "Besides, two crosstalk networks between SPGs and adjacent microenvironments including “SPGs-FGFR1/3-FGF2-pachytene/diplotene SPCs” and “SPGs-ACKR2-CCL2/3/4/5/3L1/14-EC/immune cells/perivascular cells” were detected in cryptozoospermia rather than normal patients." (PMID 37151874, 2023).
dermatofibrosarcoma protuberans (1 paper, 2026). Dermatofibrosarcoma protuberans (DFSP) is a rare infiltrating soft tissue sarcoma, generally of low grade malignancy, arising from the dermis of the skin and characteristically associated with a specific chromosomal translocation t(17;22). "In dermatofibrosarcoma protuberans (DFSP), FGF19 activates downstream signaling pathways by binding to FGFR1 and FGFR2, thereby promoting cell proliferation, survival, and migration, and ultimately driving tumor growth." (PMID 41328353, 2026).
diabetic foot ulcers (1 paper, 2023). "Specifically, monocytes/macrophages increased expression of several apoptosis genes (including BCL2, FGFR3, FGFR1, CTH, CASP3, IL19, NME5, and S100A8/9) in diabetic foot ulcers compared to monocytes/macrophages in non-diabetic wounds." (PMID 38127424, 2023).
diabetic retinopathy (1 paper, 2023). "In this study, intravitreal injection of BIBF1120 blocked the phosphorylation of VEGFR2, FGFR1, PDGFRβ, and MAPK signaling pathway proteins in a streptozotocin (STZ)-induced diabetic retinopathy mouse model." (PMID 37152616, 2023).
disc degeneration (1 paper, 2008). "Further studies linking pathogenic disc degeneration and FGF-ligand binding activity to specific FGFRs may provide important information for understanding the potential role of FGFR1 in IVD homeostasis and disc degeneration." (PMID 18435858, 2008).
Duchenne muscular dystrophy (1 paper, 2025). Duchenne muscular dystrophy (DMD) is a neuromuscular disease characterized by rapidly progressive muscle weakness and wasting due to degeneration of skeletal, smooth and cardiac muscle. "The elevated miR-214-3p had the potential to hasten FAP fibrogenesis by adjusting the FGF2/FGFR1/TGF-β axis, which shed light on new strategies for the treatment of fibrous degeneration of Duchenne muscular dystrophy (DMD) by interfering miR-214-3p." (PMID 39759120, 2025).
endometrial adenocarcinomas (1 paper, 2010). "We previously demonstrated elevated expression of the FP receptor, FGF2 and FGFR1 in endometrial adenocarcinoma." (PMID 20092633, 2010). "In addition, we found that FP receptor, FGF2 and FGFR1 co-localised within the vascular endothelial cells in endometrial adenocarcinomas suggesting that PGF2α may directly and indirectly regulate endothelial cell function." (PMID 20092633, 2010).
ependymal tumor (1 paper, 2017). A group of neoplasms which arise from the ependymal lining of the cerebral ventricles and from the remnants of the central canal of the spinal cord. "Diffuse FGFR1 immunoreactivity was detected in 42 (58%) of ependymal tumors." (PMID 28468611, 2017).
epithelioid sarcoma (1 paper, 2021). An aggressive malignant neoplasm of uncertain differentiation, characterized by the presence of epithelioid cells forming nodular patterns. "mRNA levels for FGFR1 were slightly upregulated in epithelioid sarcoma (between 1.3 and 2.2-fold), and downregulated to 46% of the initial expression in A204." (PMID 34281526, 2021).
experimental autoimmune encephalomyelitis (1 paper, 2022). An autoimmune demyelinating disease of the central nervous system that is produced experimentally in animals by the injection of homogenized brain or spinal cord in Freund's adjuvant. "Similarly, cell-specific deletion of FGFR1 in the cerebellum of an experimental autoimmune encephalomyelitis model revealed reduced expression of inflammatory cytokines, less axonal damage and myelin loss and lowered inflammation." (PMID 35455561, 2022).
familial tumoral calcinosis (1 paper, 2021). Tumoral calcinosis is a phosphocalcic metabolism anomaly, particularly among younger age groups and characterized by the presence of calcified masses in the juxta-articular regions (hip, elbow, ankle and scapula) without joint involvement. "Data from tumor-induced osteomalacia (TIO), familial tumoral calcinosis (FTC), and X-linked hypophosphatemic rickets studies have demonstrated the role of FGFR1 and its ligand FGF23 in tightly regulating phosphate balance in conjunction with the parathyroid hormone." (PMID 34199304, 2021).
fluorosis (1 paper, 2024). "The Col1a1, Bcl2, Fgfr1, Mmp9, Mmp13, Bmp2, and Bmp7 genes are the key regulatory factors in fluorosis bone metabolism." (PMID 39125380, 2024).
gastric ulcer (1 paper, 2013). An ulcerated lesion in the mucosal surface of the stomach. "We found that diminished mRNA expressions of proangiogenic growth factors (PDGFB) and their receptors (VEGFR2, FGFR1, and FGFR2) in gastric ulcer margins were well correlated with the degree of thrombocytopenia in the cirrhotic patients." (PMID 23620752, 2013). "However, mRNA expressions of FGFR1 and FGFR2 were significantly decreased in the gastric ulcer margins of the cirrhotic patients compared to those of the non-cirrhotic patients, and that the mRNA expression of FGFR was well correlated with the platelet count in cirrhotic patients." (PMID 23620752, 2013). "We found that cirrhotic patients had diminished mRNA expressions of proangiogenic growth factors (PDGFB) and their receptors (VEGFR2, FGFR1, and FGFR2) in gastric ulcer margins compared with those of the non-cirrhotic patients." (PMID 23620752, 2013). "The cirrhotic patients had diminished mRNA expressions of PDGFB, VEGFR2, FGFR1, and FGFR2 in gastric ulcer margin when compared with those of the non-cirrhotic patients (p<0.05)." (PMID 23620752, 2013).
goiter (1 paper, 2015). Enlargement of the thyroid gland usually caused by lack of iodine in the diet, hyperthyroidism, or thyroid nodules. "Analysis of FGFR1 mRNA expression revealed a noticeable increase in FA and all cancer subgroups compared to goiter tissue." (PMID 25880801, 2015). "FTC revealed lower median expression of FGFR1 than in PTC and UTC, however being still noticeably higher than in FA or goiter." (PMID 25880801, 2015).
hemangioma (1 paper, 2017). A benign vascular lesion characterized by the formation of capillary-sized or cavernous vascular channels. "Many studies have confirmed that basic fibroblast growth factor (bFGF) and its key receptor FGFR1 are highly expressed in hemangioma." (PMID 28928430, 2017). "Our results showed low expression of miR-424 in infantile skin hemangioma tissues, and that miR-424 overexpression downregulated FGFR1 expression in hemangioma-derived endothelial cells, while miR-424 inhibition upregulated FGFR1 expression." (PMID 28928430, 2017). "Many studies have reported that bFGF and its receptor FGFR1 are highly expressed in hemangiomas." (PMID 28928430, 2017).
Hypercalciuria (1 paper, 2016). "FGFR1 effects to diminish membrane expression of TRPV5 in Fgfr1DT-cKO mice likely accounts for both the inability of PTH and intracellular calcium transport pathways to compensate for the hypercalciuria." (PMID 26839958, 2016).
hyperlipidemia (1 paper, 2025). "In the present study, we found that FGF21D2D3 improved hyperlipidemia and directly bound to FGFR1 to activate AMPK, thereby reducing oxidative stress and ameliorating DCM in T2D." (PMID 40724827, 2025).
Hypertelorism (1 paper, 2025). Interpupillary distance more than 2 SD above the mean (alternatively, the appearance of an increased interpupillary distance or widely spaced eyes). "Among them, mice with a deficiency for Fgfr1, Fgfr2, Kif3a, Kras, Ptch1, Rreb1, Sos1, and Tfap2a show excessive proliferation during midfacial development, resulting in hypertelorism, suggesting that mimics of miR-383-3p and miR-6951-3p activate cell proliferation through suppression of these genes." (PMID 40787625, 2025).
hypospadias (1 paper, 2017). Hypospadias is the displacement of the urethral meatus on the ventrum of the penis. "We postulate that variants in CHH genes, in particular PROKR2, PROK2, WDR11 and FGFR1 with CHD7, may contribute to under-virilisation phenotypes including hypospadias in Indonesia." (PMID 28209183, 2017). "We conclude that variants in CHH genes, in particular PROKR2, PROK2, WDR11 and FGFR1 with CHD7, may contribute to under-virilisation phenotypes including hypospadias in Indonesian boys." (PMID 28209183, 2017).
infarction (1 paper, 2022). A localised pathological necrosis of tissue resulting from obstruction of the blood supply usually by a thrombus, an embolus, or vascular torsion. "One day after I/R injury, cardiac function, hypokinesis, and echocardiographic criteria of infarction were similarly affected in all three genotypes/conditions, suggesting that loss of cardiomyocyte FGFR1 and FGFR2 does not adversely affect cardiac function after I/R injury." (PMID 36211556, 2022).